TNF (tumor necrosis factor)
Diseases named in the same sentence as TNF in open-access papers (continued):
Sharing a sentence is not in itself a finding about the gene and the disease.
cancer (continued). "With the increasing accessibility of modern sequencing technologies and gene editing, high-throughput investigations of the TNF-α response and signaling will yield new results that enable the contextualization of TNF-α in cancer and immunology." (PMID 31263060, 2019). "Our results illustrated that the primary genes responsible for apoptosis including CASP 3, CASP 7, TNF-α, TNF-β, and MOAP1 were significantly upregulated by TIT3 treatment on HepG2 cancer cells." (PMID 31482051, 2019). "During cancer, the ROS and other stress conditions such as COX-2, PGE2, pro-inflammatory cytokines like TNF-α, IL-1β, IL-6, and another NF-kB modulator take part in facilitating the activation of nuclear translocation of NF-kB via numerous mechanisms." (PMID 31556759, 2019). "Elevated levels of TNF-α were observed in PEV-treated mice 5 weeks after administration, and antitumor activity was also evident since cancer cell proliferation was clearly inhibited by PEV." (PMID 31467867, 2019). "Cancer control group (CC) possessed relatively high secretion of IL-6, IFN-γ, MCP-1, IL-10, IL-12p70 and TNF-α from week 1 until week 4 compared with other groups." (PMID 30947706, 2019). "TNF-α mRNA ISH signal was weak and restricted to a few cells in the invasive front, where both a subset of cancer cells and stromal cells were positive." (PMID 30999696, 2019). "Cancer cells originating from the breast can form typical osteolytic metastases in the BM by secreting parathyroid hormone-related protein (PTHRP), tumor necrosis factor-α (TNFα), interleukin 6 (IL-6) and/or interleukin 11(IL-11)." (PMID 31817646, 2019). "T cells directly kill cancer-cells via the Granzyme B and Perforin pathway and/or indirectly through the secretion of IFN-γ or tumor-necrosis-factor-alpha (TNF-α)." (PMID 31533251, 2019). "Our data also show that TNFα induced phosphorylation of ERK1/2, p38 MAPK, and NF-κB in MDA-MB-231 cancer cells." (PMID 31581558, 2019). "A similar pattern of restricted expression is also observed for the other antisense TSSs: PRKN-int3AS and PRKN-int4AS in cancer cell lines, PARKN-int5AS in ARPE-19 EMT cells induced with TGFβ and TNFα, and PARKN-3′AS1 in CD14+ monocytes." (PMID 30610612, 2019). "With the increasing application of ICPIs for different cancers, in conjunction with potential risks for irAE, the liver profile should be closely monitored during treatment with ICPI as well as with anti-TNF-α agents in this patient population." (PMID 30777137, 2019). "It has recently been recognized that inflammatory cytokines, such as tumor necrosis factor-α (TNF-α), upregulate the secretion of matrix metalloproteinase-9 (MMP-9) from cancer cells and thereby promote peritoneal dissemination." (PMID 30544870, 2018). "It is known that cancer cell defects in the TNF/IFN-signaling pathway are common and that cancer cells defective of this signaling pathway become more susceptible to MYXV infection." (PMID 30595970, 2018). "We characterized spontaneous immune responses against optimized 38-mere arginase-1-derived peptide epitope in cancer patients and healthy donors using ex vivo and in vitro IFNγ ELISPOT and intracellular staining for IFNγ and TNFα." (PMID 30400835, 2018). "25(OH)D pretreatment inhibits both UV- and tumor necrosis factor alpha (TNF-α)-stimulated IL-6 production in normal cells via p38 MAPK inhibition, demonstrating its significant anti-inflammatory effects in cancer cells." (PMID 30216977, 2018). "One of the desirable effector functions of γδ T cells in cancer immunotherapy is the secretion of pro-inflammatory cytokines, such as IFN-γ and TNF-α." (PMID 29692776, 2018).
cancer (continued). "Tumor necrosis factor (TNF)-related apoptosis-inducing ligand (TRAIL) binds to death receptors and induces apoptosis in various cancer cell lines while sparing normal cells." (PMID 30651925, 2018). "In fact, it has been observed that the modulation of c-Jun or Stat5a activation also modulates TNF shedding elicited by BPA and NP in cancer cell lines." (PMID 30065191, 2018). "Furthermore, considering that cell differentiation and apoptosis process could be controlled by proinflammatory cytokines, the next step was to evaluate the main proinflammatory cytokines described as responsible for the depletion of AT during cancer cachexia, in particular, IL-6 and TNF-α." (PMID 30094378, 2018). "TNFα increases the expression of MMP-3 and MMP-13 in HepG2 cells and enhances cancer cell migration by activation of the extracellular signal-regulated kinase/ NF-κB pathways." (PMID 30591653, 2018). "The matrix metalloproteinase-9 (MMP9) is most likely involved in the TNF-α-mediated fusion of human M13SV1-Cre breast epithelial cells and human MDA-MB-435-pFDR1 cancer cells." (PMID 29636110, 2018). "Osteoclastic activity is under the influence of tumor necrosis factor alpha (TNF alpha) and other cytokines that are secreted by the cancer cells." (PMID 30443456, 2018). "Pro-inflammatory cytokines like TNF-α, IFN-γ and GM-CSF upregulate death receptors on cancer cells and induce apoptosis." (PMID 30237863, 2018). "IL-1β and TNFα induced IL-18 release upregulating the expression of VCAM-1 on hepatic sinusoidal endothelium (HSE) and thereby promoting cancer cell adhesion and liver metastases." (PMID 30042333, 2018). "Adipocytes secrete adipokines (LEP, ADIPOQ, IL-6, IL−1β, TNFα), MMPs, and PAI-1, to enhance cancer progression." (PMID 29881724, 2018). "Despite the fact that information relative to its role in cancer is still limited, it was first shown that RTN3 overexpression triggers tumor necrosis factor-related apoptosis-inducing ligand (TRAIL)-, tumor necrosis factor (TNF)-α and Fas-dependent apoptosis." (PMID 30250843, 2018). "Transforming growth factor-β (TGF-β), platelet-derived growth factor (PDGF), tumor necrosis factor (TNF), stromal cell-derived factor 1 (SDF1) and fibroblast growth factor 2 (FGF2) are key mediators of fibroblast activation in cancer development." (PMID 30477536, 2018). "In particular, tumor necrosis factor-α (TNF-α) and other inflammatory cytokines have been shown to participate in the initiation and progression of cancer." (PMID 30544870, 2018). "At the protein level, cancer cells showed only slight and focal cytoplasmic IFN-γ specific immunostaining and slight diffuse positivity along cell membranes to anti-TNF-α antibody." (PMID 29896191, 2018). "The agonists for some of the co-stimulating receptors of the immunoglobulin (CD28, ICOS) and tumor necrosis factor (4-1BB, CD27, GITR, OX40) superfamily have been evaluated for cancer therapy." (PMID 29857493, 2018). "Some protein drugs, such as tumor necrosis factor alpha (TNF-α), INF-γ, and IL-2, have been widely used in clinical cancer treatment." (PMID 30483132, 2018). "Our data demonstrate that NF-κB inhibition can block the acidic bile-induced overexpression of TNF-α, NF-κB transcriptional factor RELA(p65), and cancer related cytokines, IL-1β and IL-6." (PMID 29464041, 2018). "Along the same line, increased circulating levels of tumor necrosis factor α (TNFα), interleukin-6 (IL-6), γ-interferon (INF), and, more recently, growth and differentiation factor 15 (GDF15) have been reported in cachectic cancer patients." (PMID 29785246, 2018).
cancer (continued). "Whereas TNF-α acts as an initiator and modulator of tumorigenesis has been intensively studied, the role of another member of the TNF-superfamily during cancer development, Lymphotoxin-α (alias TNF-β) needs to be further characterized." (PMID 30002278, 2018). "Because our experiments demonstrated that TNF-α potentiated MMP-9 secretion from both mesothelial cells and cancer cells, we next addressed the effect of the exogenous addition of MMP-9 on the invasive behavior of cancer cells." (PMID 30544870, 2018). "Other potent inducer of PD-L1 is tumor necrosis factor α (TNF-α), functional both in monocytes and in cancer cells." (PMID 30140263, 2018). "KEGG analysis surfaced that DEGs were essentially abundant in pathways in cancer, PI3K-Akt signal pathway, Jak-STAT signal pathway, TNF signaling pathway, and mTOR signaling pathway." (PMID 29854840, 2018). "Hypertonicity robustly enhanced cytotoxicity of tumor necrosis factor (TNF)-related apoptosis-inducing ligand (TRAIL) and other DR ligands in various cancer entities." (PMID 29706657, 2018). "In fact, TNF-α has been shown to positively induce MMP9 expression and secretion in various cancer cells to promote their metastatic ability." (PMID 29748481, 2018). "Given that TNF-α is a strong stimulatory factor in various cancer cell lines, previous studies reported that RSV inhibits TNF-α-induced cell invasion in many types of cancer cells through inhibiting NF-κB." (PMID 29925765, 2018). "The regulation of essential cancer-related pathways, such as Wnt, Hippo, HIF-1, TNF and PI3K/AKT, etc., was also found in our proteomics results." (PMID 29867083, 2018). "The results of this review show that açaí acts in the inflammatory processes involved in induced-cancer in animals by decreasing the levels of IL-1β, IL-5, IL-6, IL-8, COX-2, TNF-α and MPO and increasing the levels of IFN-γ." (PMID 29966007, 2018). "In fact, some cancer cell lines (including MDA-MB-435, the parental cell line of MDA-MB-435S) have been reported to express the transmembrane form of TNF-α, tmTNF-α54." (PMID 29748553, 2018). "Tumor necrosis factor alpha (TNF-α) and IL-6 are two of the best-studied pro-inflammatory and pro-tumorigenic cytokines, the expression of which are elevated in many different cancers." (PMID 30563089, 2018). "It was reported that tumor necrosis factor alpha (TNF-α), as one of the major inflammatory cytokines secreted by macrophages, plays an important role in maintaining cancer cell evasion from immune system." (PMID 29910728, 2018). "We have recently shown that NK cells specifically target and kill cancer stem cells/undifferentiated tumors, and are activated to secrete IFN-γ and TNF-α in order to drive the differentiation of tumors." (PMID 29977235, 2018). "Our results show that cordycepin can inhibit PD-L1 expression in cancer cells, and another ingredient of CMP, EPS can significantly increase TNFα production in peritoneal macrophages." (PMID 29212184, 2017). "Targeting the procarcinogenic products of inflammation like free radicals, arachidonic acid metabolites, NFκB transcription factor, TNF-alpha (TNF-α), CXC chemokines and AKT can be an important approach to halt cancer development and progression." (PMID 28724427, 2017). "For example, cancer cells stimulate expression of adipokines and adipocytokines (including IL-6, IL-1β, CCL2, CCL5, TNF-α, MCP-1, leptin), proteases, and inhibitors (e.g., MMP-11, PAI-1)." (PMID 28101337, 2017). "Expression of the cell adhesion molecule (CAM), Sialyl Lewis X (CD15s) correlates with cancer metastasis, while expression of E-selectin (CD62E) is stimulated by TNF-α." (PMID 28698503, 2017). "We demonstrated in this study that TNF-α-pretreated hMSCs secreted high levels of CCL5, through which communicated with CRC cells and enhanced cancer EMT and progression." (PMID 28542126, 2017).
cancer (continued). "The well-documented cancer-related genes NOTCH1, CDKN1A, EGR1, AKT3, TNF, MMP9, and SMARCA4 are located in the center of this newly constructed subnetwork." (PMID 28500316, 2017). "Potent αDC1s, induced by cytokine cocktails containing IL-1β, TNF-α, INF-α, IFN-γ, and poly I:C, generate strong functional cytotoxic T lymphocytes (CTLs) in several type of cancers and are, on average, 20-fold more active than conventional DCs." (PMID 28088784, 2017). "The fact that IRF-2 expression was often elevated in cancer cells, and elevated IRF-2 levels would enhance NF-κB activity when delivered an activation, such as TNF-α." (PMID 28465494, 2017). "Therefore we quantified the amount of some pro-inflammatory cytokines (IL1β, TNFα, IL12-p70, IL6, IL8, IL10) by CBA and found that the SCM was highly enriched in IL6 and IL8, two pleiotropic pro-inflammatory cytokines that have been implicated in cancer progression." (PMID 28472950, 2017). "Our study showed that doxycycline suppressed both LPA- and TNFα-induced nuclear translocation of NF-κB and blocked the LPA-induced secretion of IL-6, CCL2 and CXCL2 in cancer cells." (PMID 28178994, 2017). "Tumor necrosis factor alpha (TNF-α), a member of the TNF/TNFR cytokine superfamily, is assocated with chronic inflammation and the development of cancer." (PMID 28030810, 2017). "In cancer cells, SMAC mimetic (SM)-mediated IAP depletion induces tumor necrosis factor (TNF) secretion and simultaneously sensitizes for TNF-induced cell death." (PMID 28771230, 2017). "The candidate genes including BGN, MMP1, LGALS1, SERPINB5, and TM4SF4 probably correlated with cancer development and the EMT program mediated by the integrated pathway of TGFβ/Snail with TNFα/NFκB." (PMID 28687755, 2017). "Since pro-inflammatory cytokines play a critical role in the onset of cancer cachexia, we measured mRNA levels of IL6, TNFα, IL1β, and PTHrP32,33 in C26 tumors isolated from mice treated with vehicle, (−)-JQ1 and (+)-JQ1 (20 and 50 mg/kg/day)." (PMID 29167426, 2017). "Therefore, GSC might be applied as a TNFα adjuvant for cancer therapy." (PMID 29379440, 2017). "Several lines of evidence have demonstrated that key molecules that are involved in cancer-related inflammation include NF-kB, STAT3, and major inflammatory cytokines, such as IL-1b, IL-6, IL-23, and TNF-a." (PMID 29232409, 2017). "Neuroinflammation in the context of cancer and cancer-treatment is frequently characterized by changes in expression of proinflammatory cytokines such as IL- 1β, IFN-γ IL-6, and TNF-α." (PMID 27893434, 2017). "Tumor necrosis factor-α (TNF-α), an important factor in systematic inflammation, is reportedly involved in several cancer types." (PMID 28575042, 2017). "Therefore, AG may be used as a TNFα adjuvant for cancer therapy." (PMID 28199969, 2017). "We further included the 9 known cancer-signaling pathways from the NetPath database, namely, EGFR1, FSH, IL-1, IL-4, IL-5, Leptin, RANKL, TNF-alpha, and TSH." (PMID 29190299, 2017). "Tumor necrosis factor-related apoptosis-inducing ligand (TRAIL), a member of the tumor necrosis factor (TNF) superfamily, exhibits anti-cancer activity and selectively induces apoptosis in various cancer cells, but not in normal cells." (PMID 29348850, 2017). "Autocrine/paracrine regulation of TNF-α has also been observed in C2C12 myoblasts following serum restriction and in various other cell lines and tissues, including cancer cells, immune cells, and microglia." (PMID 28742154, 2017). "As a main mode of cell death mediated by SMCs relies on the engagement of the apoptotic pathways in cancer cells on stimulation by TNF-α, we accordingly analysed the expression level of TNF-α in T-cells." (PMID 28198370, 2017). "The conditioned medium from MSCs pretreated by TNF-α and IFN-γ was gathered and used for cancer cell migration assay." (PMID 29088737, 2017).
cancer (continued). "MDA-MB-231 and A549 cancer cells were treated with TGF-β1, TNF, or their combination and whole-cell lysates were probed for signaling markers." (PMID 28423685, 2017). "The role of TNF has been shown to be critical for the generation of MDSC during several pathologies, including cancer and chronic inflammation." (PMID 28890718, 2017). "Recently, we demonstrated that a self-limiting cytokine storm that includes TNF-α and TRAIL can be generated with immunostimulatory agents to safely synergize with SMCs to cure mice of cancer and that this outcome depends largely on innate immunity." (PMID 28198370, 2017). "Tumor necrosis factor (TNF)-related apoptosis-inducing ligand (TRAIL), also known as APO-2 ligand and TNFSF10, is a promising anti-cancer agent that belongs to the TNF superfamily." (PMID 28209994, 2017). "Thus, in theory, TNF-α antagonists may either promote or inhibit cancer growth." (PMID 28222785, 2017). "Tumor necrosis factor (TNF)-related apoptosis-inducing ligand (TRAIL) is known for specifically killing cancer cells, whereas in resistant cancers, TRAIL/TRAIL-R can promote metastasis via Rac1 and PI3K." (PMID 28212753, 2017). "In this study, we are interested in the significance of inflammatory factor TNF-α on oncoprotein HBXIP in the links between inflammation and cancer." (PMID 28938560, 2017). "Proinflammatory cytokines IL-6, TNF-α, and TGF-β have been widely examined for their regulation of cancer cachexia." (PMID 28785374, 2017). "TNF‐α can control the expression of multiple other cytokines and TNF‐neutralizing agents are used to treat cancer." (PMID 28599100, 2017). "Thus, our results together with theses finding suggested that activation of Wnt/β-catenin signaling pathway could control the expression of syncytin-1, and contribute to the enhancement in cancer-endothelial cell fusion induced by the pro-inflammatory factor TNF-α." (PMID 28112190, 2017). "Further, COP9 signalosome 5 (CSN5) stabilized programmed cell death-ligand-1 (PD-L1) plays important role in TNF-α-induced cancer immunosuppression in TME, and curcumin can inhibit CSN5, leading to sensitization of cancer cells to immunotherapy." (PMID 28273819, 2017). "TLR7/8 activation promotes anti-cancer host defense through the secretion of pro-inflammatory cytokines and chemokines, including IFN-α, IFN-γ and tumor necrosis factor (TNF)-α, acting on DC, macrophages and T cells, especially of the Th1 subset." (PMID 28829805, 2017). "Fat cells secrete the inflammatory mediators tumor necrosis factor-alpha (TNF-α) and interleukin 6 (IL-6), which promote cancer induction." (PMID 26977321, 2016). "According to the results, a statistically significant increase of IL-2, IL-10, TNF-α, IFN-γ, and IL-17 was observed in patients with cancer compared with the control group." (PMID 26905729, 2016). "TNF can induce the expression of transforming growth factor alpha (TGF α) and epidermal growth factor receptor (EGFR) in cancer cells." (PMID 27821804, 2016). "Inflammatory cytokine levels such as those of IL-6 and TNF-α were significantly increased in KRAS-induced ascites, suggesting that inflammation plays a central role in KRAS-induced cancer progression." (PMID 27483433, 2016). "In a larger sample size, (54 patients and 35 cancer-free controls), we found IL1RA, MCP-1, and TNF were present at significantly higher levels in samples with high neutrophil cytotoxicity relative to samples with low neutrophil cytotoxicity." (PMID 28721376, 2016). "These activities also contributed to AECHL-1 mediated suppression of TGF-β/TNF-α induced Epithelial to Mesenchymal Transition (EMT) and cancer stem cell characteristic." (PMID 27974826, 2016). "Regarding the cytokines evaluated in the serum of individuals with and without cancer, significant differences were observed among individuals with cancer for IL2, IL10, TNF-α, IFN-g and IL17." (PMID 26905729, 2016).